ENSG00000201245
Synonyms: LOC124900342
Gene: Small nucleolar RNA gene on chromosome 13 (99,783,857 to 99,783,983, reverse strand). Ensembl gene ENSG00000201245.
Gene Ontology:
Biological process: RNA processing
Cellular component: nucleolus
Homologues: Paralogues in human: SNORA25B (85% identical), SNORA25 (84% identical).